IL36G (interleukin 36 gamma)
Diseases named in the same sentence as IL36G in open-access papers (continued):
Sharing a sentence is not in itself a finding about the gene and the disease.
atopic dermatitis (2 papers, 2021 to 2025). "Studies have shown that the mRNA expression of IL‐36G is significantly upregulated in the eczematous skin areas of patients with atopic dermatitis." (PMID 40159643, 2025). "Further analysis of cytokines and their receptors, along with their correlation with infiltrating immune cells, identified IL36G‐expressing monocytes as a key target in atopic dermatitis." (PMID 40159643, 2025). "Correlation analysis between cytokines and immune cells confirmed that IL‐36G is specifically expressed in monocytes in atopic dermatitis, thereby identifying specific targets for atopic dermatitis." (PMID 40159643, 2025). "This indicates high affinity and suggests that these drugs may exert therapeutic effects on atopic dermatitis by targeting IL‐36G." (PMID 40159643, 2025). "Finally, the biological function and molecular mechanisms of IL36G monocytes in atopic dermatitis require further investigation, and the efficacy of the two predicted IL36G‐targeting drugs also awaits validation." (PMID 40159643, 2025). "Finally, we further investigated the correlation of cytokines and their receptors with immune cells, finding that IL‐36G was highly expressed specifically in monocytes (p < 0.001), indicating that IL‐36G‐expressing monocytes may be a core target in atopic dermatitis." (PMID 40159643, 2025). "The reported list of inflammatory mediators found in atopic dermatitis includes S100A7, S100A8 S100A9, CCL2, CCL3, IL36A, IL36G, and IL36RN." (PMID 34925353, 2021).
breast carcinoma (2 papers, 2021 to 2022). "And IL36G has been identified to have anti-tumor effects in breast cancer and melanoma." (PMID 34852762, 2021).
Cachexia (2 papers, 2025 to 2026). Severe weight loss, wasting of muscle, loss of appetite, and general debility related to a chronic disease. "This is consistent with the idea that muscle wasting in cachexia is a complex process, influenced by multiple mechanisms, possibly including other non-immune cell and/or immune cell-derived factors such as activin A and IL36G, as recently proposed." (PMID 40474277, 2025).
myeloid leukemia (2 papers, 2019 to 2023). A clonal proliferation of myeloid cells and their precursors in the bone marrow, peripheral blood, and spleen. "The physically closest SNP previously discussed is rs1374284 that was associated with therapy-related myeloid leukemia susceptibility and is located 10.3 kb from IL36G in 3′ direction." (PMID 30634937, 2019). "IL-1RAP is a transmembrane protein that potentiates multiple inflammatory signaling pathways, including IL-1, IL-33, IL-36G, and stem cell factor, and it has the unique feature of being expressed at higher levels in stem and progenitor cells from myeloid leukemia patients compared to normal HSPCs." (PMID 37498674, 2023).
Obesity (2 papers, 2022 to 2025). Accumulation of substantial excess body fat. "Since VAT represents a crucial tissue in the obesity-associated chronic inflammation state as well as in colon carcinogenesis, gene expression levels of IL36G and IL36R in VAT were analysed." (PMID 40268791, 2025). "We also investigated the impact of inflammation-related factors altered in obesity on the expression of IL36G and IL36R in tumour cells." (PMID 40268791, 2025). "The role of visceral adipocytes as a source of pro-inflammatory factors was further corroborated by our observation that ACM from patients with obesity significantly increased IL36G expression in tumour cells." (PMID 40268791, 2025). "For this reason, we herein evaluated the effects of ACM obtained from patients with normal-weight and with obesity on the expression of IL36G and IL36R in tumour cells." (PMID 40268791, 2025). "Leptin levels are elevated in patients with obesity and, after the stimulation of tumoral cells with this hormone, IL36G levels significantly increased (P < 0.05)." (PMID 40268791, 2025). "Knowing the role of IL-36 in the obesity-associated low-grade inflammation and the importance of chronic inflammation in the physiopathology of cancer, we hypothesised that increased expression levels of IL36G in dysfunctional AT in obesity may favour CC development by increasing inflammation." (PMID 40268791, 2025). "We also investigated the effects of other inflammatory factors altered in obesity on IL36G and IL36R expression in tumour cells." (PMID 40268791, 2025). "A diet-induced obesity mice model was used to corroborate human findings regarding the expression of IL36G in adipose tissue and liver." (PMID 35222417, 2022). "We showed, for the first time, increased (P<0.05) mRNA expression of both, IL36G and IL36R in VAT in obesity-associated T2D with their gene expression levels being also significantly associated between them (r=0.32; P=0.042)." (PMID 35222417, 2022). "To gain a better understanding of how IL-36γ might impact the pathogenesis of obesity and metabolic diseases, we examined the expression levels of IL36G and its main receptor, IL36R, in metabolically active tissues." (PMID 35222417, 2022). "The increased expression of IL36G in VAT of patients with obesity and CC may reflect a dysregulated immune response, exacerbating both local and systemic inflammation and contributing to the inflammatory microenvironment surrounding tumours, potentially promoting carcinogenesis." (PMID 40268791, 2025). "A remarkable point to consider is that we measured IL36G and IL36R gene expression in VAT samples from well-characterised patients with obesity and CC." (PMID 40268791, 2025). "Consistently, IL36G expression was upregulated by hypoxia, inflammation-related factors (LPS, TNF-α and leptin) and by the adipocyte secretome from patients with obesity in HT-29 cancer cells." (PMID 40268791, 2025). "The upregulated gene expression levels of IL36G in the VAT and PBMC in obesity strengthen the role of the cytokine in inflammation." (PMID 35222417, 2022). "In this context, a marked increase (P<0.01) in the expression levels of IL36G was shown in PBMC in obesity with no changes in IL36R transcript levels being observed." (PMID 35222417, 2022). "We aimed to investigate whether the upregulated IL36G and IL36R in obesity are derived from adipocytes or SVFC." (PMID 35222417, 2022).
AIDS (1 paper, 2020). A syndrome resulting from the acquired deficiency of cellular immunity caused by the human immunodeficiency virus (HIV). "The IL-1 cytokine family (IL-1α, IL-1β, IL-1Ra, IL-18, IL-36Ra, IL-36α, IL-37, IL-36β, IL-36g, IL-38, IL-33) was defined to be principally responsible for the inflammatory nature of polygenic AIDs." (PMID 33708123, 2020).
cervical cancer (1 paper, 2020). A primary or metastatic malignant neoplasm involving the cervix. "The aberrant expression of many mRNAs, including FGFR3, CTGF, TP63, IL36G, ADH7, SPINK5, and so on, have also been identified in cervical cancer." (PMID 32123519, 2020).
colorectal cancer (1 paper, 2021). A primary or metastatic malignant neoplasm that affects the colon or rectum. "Transcriptomic data analysis of various immune cell populations purified from human colorectal cancer (CRC) microenvironment has shown that IL36G is expressed at significantly higher levels in M1-Mφs compared to all other immune cells, including M2-Mφs." (PMID 34281268, 2021).
esophageal cancer (1 paper, 2026). A primary or metastatic malignant neoplasm involving the esophagus. "Further in vitro experiments demonstrated that silencing IL1RN and IL36G in macrophages markedly suppressed the malignant phenotypes of esophageal cancer cells." (PMID 41704537, 2026).
Hyperkeratosis (1 paper, 2021). Hyperkeratosis is a histopathological term defining a thickened stratum corneum and may be present in many different skin conditions, with many possible overlaps. "The overlapping DEGs included genes associated with hyperkeratosis (upregulated LCE3E and TMEM45A), wound healing (upregulated KRT17, IL36G, TNC, and TGFBI), barrier defects (downregulated FRAS1 and BCL11A), and response to infection (upregulated IL36G, ADAP2, DFNA5, RFTN1, LITAF, and TMEM173)." (PMID 34506598, 2021).
influenza (1 paper, 2019). An acute viral infection of the respiratory tract, occurring in isolated cases, in epidemics, or in pandemics; it is caused by serologically different strains of viruses (influenzaviruses) designated A, B, and C, has a 3-day incubation period, and usually lasts for 3 to 10 days. "Here, we report that a designed truncated Interleukin-36 gamma (IL-36 gamma) encoded plasmid can act as a potent adjuvant for several DNA-encoded vaccine targets including human immunodeficiency virus (HIV), influenza, and Zika in immunization models." (PMID 31121939, 2019).
lymphoma (1 paper, 2024). A malignant (clonal) proliferation of B- lymphocytes or T- lymphocytes which involves the lymph nodes, bone marrow and/or extranodal sites. "To address this question, we validated eight plasma proteins (IL-17A, F5, FLT4, SFTPB, and GNPTG in lymphoma, TNFSF12, CCL3, and KIT in NSCLC) for response prediction and three plasma proteins (IL36G, SERPINC1, and LTA) for relapse monitoring." (PMID 38349411, 2024).
oral lichen planus (1 paper, 2023). Oral lichen planus is a chronic inflammatory oral condition of unknown aetiology characterized by T-cell-mediated chronic immune response and abnormal epithelial keratinization cycle. "In a study of oral lichen planus (OLP) and normal skin tissues performing RNA-seq, molecules related to wound healing, KRT17, IL36G, TNC and TGFBI genes were significantly upregulated in OLP tissues." (PMID 37929023, 2023).
periodontitis (1 paper, 2024). An acute or chronic inflammatory process that affects the tissues that surround and support the teeth. "IL1 superfamily members IL1A, IL1B, and IL36G were upregulated in periodontitis in both the basal and suprabasal layers of the JK; further, though previously reported, we observed concomitant expression of these genes in the peri-junctional stroma." (PMID 38876998, 2024).
Pruritus (1 paper, 2023). Pruritus is an itch or a sensation that makes a person want to scratch. "It was shown that the expression of genes encoding inflammatory mediators such as CCL4, CCL7, CCL8, CCL20, interleukin-19 (IL-19), IL-20, IL-26, IL-36A, IL-36G, and TNF-α) was unique to psoriatic skin with pruritus." (PMID 37834183, 2023).
skin tumours (1 paper, 2019). "The rabbit skin tumours induced via blood infection displayed decreased expression of SLN, TAC1, MYH8, PGAM2, and APOBEC2 and increased expression of SDRC7, KRT16, S100A9, IL36G, and FABP9, as seen in tumours induced by local infections." (PMID 31340720, 2019).
vitiligo (1 paper, 2021). Generalized well circumscribed patches of leukoderma that are generally distributed over symmetric body locations and is due to autoimmune destruction of melanocytes. "The upregulated genes in vitiligo lesional skin include markers of inflammation (such as MARCO, NLRP10, PTGS2, and IL36G), oxidative response genes (DUOXA2), and NK cell receptors (NCR3LG1), revealing presence of activated immune response in vitiligo lesions." (PMID 33815367, 2021).
tumor (13 papers, 2015 to 2026). "Furthermore, we identified a significant increase in interleukins and tumour necrosis factors, including IL‐1a, IL‐1b, IL‐6, IL‐17C, IL‐32, IL‐36G and TNF, along with its associated enzyme." (PMID 39865778, 2025). "Among these genes, IL1RN and IL36G function as key regulators whose silencing inhibits M2 polarization and attenuates tumor proliferation, invasion, migration, and epithelial-mesenchymal transition." (PMID 41704537, 2026). "IL-36G and APOH have also been associated with different types of tumour development and progression." (PMID 36065314, 2022). "What’s more, IL36G has been shown to enhance the effector function of immune cells such as NK cells, so that the environment is transformed into the tumor destruction." (PMID 34852762, 2021). "Interestingly, leptin enhanced the IL36G expression in tumour cells in our in vitro study." (PMID 40268791, 2025). "Finally, IL36G may contribute to the growth of anti-tumor and metastasis of tumor." (PMID 34852762, 2021). "Increased gene expression levels of IL36G in VAT from patients with OB and CC may promote a pro-inflammatory microenvironment favourable for tumour progression and migration." (PMID 40268791, 2025). "The hub genes in nontumour tissues are GADD45A and IL-36G, while the hub genes in tumour tissues are POSTN and APOH." (PMID 36065314, 2022). "Consistent with RNA-seq data, the expression of SLN, TAC1, MYH8, and PGAM2 were down-regulated, whereas SDRC7, KRT16, S100A9, IL36G, and FABP9 were up-regulated in both blood (Animal #9, #11, and #12) and skin (Animal #6, #7, and #8)-induced tumours relative to normal skin controls." (PMID 31340720, 2019).
infection (6 papers, 2015 to 2025). The state of being infected such as from the introduction of a foreign agent such as serum, vaccine, antigenic substance or organism. "IL-36γ mRNA levels were transiently increased 2 weeks after infection (P = 0.057), and IL-36g mRNA was present in lung granulomatous lesions after M. bovis BCG infection, as shown by in situ hybridization." (PMID 25950182, 2015). "Moreover, IL36G is one of the canonical molecules triggered by infection with uropathogenic E. coli in the mouse bladder." (PMID 34506598, 2021). "In addition, several DEGs, including IL36G, ADAP2, DFNA5, RFTN1, LITAF, and TMEM173, that were commonly upregulated in the partial sets of the epithelium and mucosa are associated with the response to infection." (PMID 34506598, 2021). "At 24 hr post-infection, increases in IL-36RN and IL-36G expressions were detected in both H37Rv- and MKR-infected cells, albeit more increase in IL-36RN and less increase in IL-36G expressions were seen in the MKR-infected macrophages when compared to that of H37Rv-infected cells." (PMID 36242542, 2022).
cancer (4 papers, 2023 to 2026). A tumor composed of atypical neoplastic, often pleomorphic cells that invade other tissues. "Additional hits were Lysozyme C, Bleomycin hydrolase, Interleukin-36 gamma, AMBP (alpha-1-microglobulin/bikunin precursor), Ganglioside GM2 activator, and Beta globin—which are indicative of cancer cell survival." (PMID 40725142, 2025).
inflammation (2 papers, 2024 to 2025). Aberrant reaction of the microcirculation characterized by movement of fluid and leukocytes from the blood into extravascular tissues. "This is illustrated by their strong expression of pro-inflammatory mediators including chemokines (e.g. Ccl3, Ccl4) and members of the IL-1 family, such as Il1f9 (encoding for IL-36γ) that was specifically expressed by neutrophils and recently identified as an amplifier of pulmonary inflammation." (PMID 38348034, 2024). "Pro-inflammatory IL36A, IL36B, and IL36G were increased in NEC and IL-36γ-deficient mice were protected from T-cell driven intestinal inflammation." (PMID 41283989, 2025).
bacterial infection (1 paper, 2025). "Coupled with the increase in S100A7, IL36G, and PI3, which are associated with bacterial response, these data indicate a compromised epidermal barrier and bacterial infection in high bleeders." (PMID 41156831, 2025).
IL36G also shares sentences with these, for which no sentence is quoted: atherosclerosis (3 papers); Colon cancer (2); psoriatic arthritis (2); pustular psoriasis (2); bacterial vaginosis (1); cardiac hypertrophy (1); cerebral malaria (1); coronary artery calcification (1); coronary artery disease (1); Erythema (1); Gastric Metaplasia (1); inflammatory bowel disease (1); melanoma (1); metabolic disease (1); mitral annular calcification (1); neutropenia (1); osteoarthritis (1); primary biliary cholangitis (1); type 2 diabetes mellitus (1); urticaria (1).